PTENP1 (phosphatase and tensin homolog pseudogene 1)
Diseases named in the same sentence as PTENP1 in open-access papers (continued):
Sharing a sentence is not in itself a finding about the gene and the disease.
tumor (continued). "Next, the antitumor activity of ADR against PTENP1-driven tumor growth in nude mice was also assessed." (PMID 31196157, 2019). "The pseudogene PTENP1 plays a role in inhibiting tumor growth by negatively regulating the expression of PTEN." (PMID 30881525, 2019). "In the present study, we found that ectopic expression of PTENP1 led to inhibition of the tumor growth, colony formation, invasion and xenograft tumor growth of BC." (PMID 31196157, 2019). "PTENP1 over-expression resulted in the growth inhibition of cancer cells both in vitro and in vivo, suggesting that PTENP1 played a tumor suppressive role in HCC." (PMID 31196157, 2019). "Consistent with our previous findings in vitro, exosomal PTENP1 also repressed tumor growth in vivo." (PMID 30285771, 2018). "Next, we conducted a subgroup analysis by clinicopathologic features (tumor grade, tumor stage and clinical grade) and found that exosomal PTENP1 levels gradually decreased with the deterioration of clinicopathologic features." (PMID 30285771, 2018). "The tumor tissues of mice inoculated in PTENP1 vector and PTENP1-Exos presented an increased expression of PTENP1." (PMID 30285771, 2018). "Given that PTEN is a tumour suppressor gene, the PTENP1 pseudogene has been described as a tumour suppressor lncRNA pseudogene." (PMID 29455665, 2018). "As the first pseudogene identified to be able to regulate its parent gene PTEN through ceRNA mechanism, PTENP1 is a tumor suppressor." (PMID 30071685, 2018). "Several other studies support the notion that PTENP1 is a tumor suppressor in variety of cancers, including esophageal squamous cell carcinoma, oral squamous cell carcinoma head and neck squamous cell carcinoma and melanoma." (PMID 30071685, 2018). "In line with in vitro analysis, PTENP1 overexpression significantly decreased the mean tumor weight and average tumor volume as compared with NC group." (PMID 30285771, 2018). "Activation of PTENP1 partially inhibited the suppression of PTEN by miR-21 in oral squamous cell carcinoma (OSCC) tumor xenografts." (PMID 30217221, 2018). "The lncRNA PTENP1 exerts its tumor suppressor function by inhibiting miR-193a-3p in the RISC complex." (PMID 29296207, 2017). "An increasing number of studies have shown that PTENP1 functions as a competing endogenous RNA to suppress tumour progression." (PMID 28112249, 2017). "Based on the periodic observation of tumor growth, tumor volumes in the PTENP1-plasmid group were significantly smaller than those in the NC group." (PMID 29296207, 2017). "In the present study, we found that ectopic expression of PTENP1 leads to inhibition of the tumour growth, colony formation, migration and xenograft tumour growth of HNSCC." (PMID 28112249, 2017). "To decipher the influence of PTENP1 on the biological functions in HNSCCs, we evaluated the proliferation of tumour cells by the MTT assay." (PMID 28112249, 2017). "Here, we evaluated the possible function of PTENP1 and found that it acts as a potential tumour suppressor due to a reduction in the copy number, independent of PTEN, in HNSCCs and can serve as an independent prognostic factor in patients with HNSCC." (PMID 28112249, 2017). "While being protein non-coding, PTENP1 transcripts are biologically active and tumor suppressive in various solid cancers." (PMID 28213783, 2017). "Pseudogene PTENP1 exerted a growth-suppressive role in tumor through a regulatory function of PTEN, which as a decoy for PTEN-related miRNAs such as miR-17, miR-19b, and miR-20a and competed with these miRNAs." (PMID 29291003, 2017). "In HCC, miR-193a-3p is a direct target of PTENP1, acting as a tumor suppressor by modulating downstream targets such as the PTEN/Akt signaling pathway." (PMID 29296207, 2017). "Injection of the lncRNA PTENP1-expressing vectors into mice bearing HCC tumors effectively mitigated the tumor growth, suppressed intratumoral cell proliferation, elicited apoptosis, autophagy and inhibited angiogenesis." (PMID 26758762, 2016).
tumor (continued). "PTENP1, a pseudogene of the tumour-suppressor PTEN (phosphatase and tensin homologue), was among the first reported noncoding miRNA sponges with a function in cancer." (PMID 26975529, 2016). "PTENP1 tumor suppressive properties were due in part to sequestration of miR-21, providing additional support for the functional relevance of PTENP1 as a tumor suppressive ceRNA for PTEN." (PMID 25888444, 2015). "By binding miRNAs, PTENP1 transcripts reduce the effects of translational repression on PTEN therefore allowing expression of this tumor suppressor." (PMID 21489289, 2011). "In cancer, specific mutations inactivate these miRNA binding sites in PTENP1, therefore reducing the translation of PTEN and promoting tumor growth." (PMID 21489289, 2011). "Since PTEN (and regulatory RNAs such as PTENP1 or miR-96-5p) are actively packed into these EVs and remain functionally intact, measuring their levels in patient fluids can provide a real-time picture of tumor suppressor activity and changes in the TME." (PMID 40877546, 2025). "Interestingly, PTENP1 expression was downregulated comparing primary tumors with adjacent normal tissue (similarly as in our study) but upregulated between primary tumor and normal tissue." (PMID 38277283, 2024). "It has been reported that exosomal lnc PTENP1 in tissues and plasma of bladder cancer patients exhibits a strong correlation with tumor pathological features such as tumor morphology, size and weight, and maintains a significant negative correlation with clinical grade of the disease,(P < 0.05)." (PMID 39040108, 2024). "The results indicated the tumor suppressor roles of PTENP1, GNG12-AS1, MEG3 and MAGI2-AS3." (PMID 38277283, 2024). "PTENP1 inhibited tumor proliferation, colony formation, invasion, and tumor growth in BC." (PMID 37596669, 2023). "Additionally, considering the higher methylation of PTENP1 in older women and its tumor-suppressive role, it has been suggested that PTENP1 methylation is associated with subsequent elevation of its expression." (PMID 38203493, 2023). "Down-regulation of these miRNAs by PTENP1 induces anti-tumor effects." (PMID 35655204, 2022). "Overexpression of a PTENP1 transgene could restore its tumor suppressor activity and inhibit tumor growth." (PMID 33466728, 2021). "Therefore, in this study we investigated in details methylation status of PTENP1 in normal, hyperplastic and tumor tissues of endometrium obtained from women of various age groups." (PMID 33481830, 2021). "Moreover, PTENP1, too, acts as a tumor-suppressive factor in RCC by acting as a competing endogenous RNA for miR-21, which would otherwise promote cell proliferation, migration, and invasion by the suppression of PTEN, an important tumor suppressor." (PMID 33042985, 2020). "PTENP1 might act as a tumor suppressor by endogenously competing with miR-20a, recovering the suppressed function of PTEN in BC." (PMID 31196157, 2019). "PTENP1 showed a lower level in tumor tissues relative to the paired adjacent tissues." (PMID 31196157, 2019). "The tumor tissues of nude mice injected with PTENP1-Exos also attenuated tumor size and weight." (PMID 30285771, 2018). "There is accumulating evidence that lncRNA PTENP1 possesses a tumour suppressive role in several cancers and has been downregulated or deleted in numerous cancers such as prostate, gastric carcinoma, clear-cell renal carcinomas, lung cancer, melanoma and colon cancer." (PMID 29455665, 2018). "In this study, we determined the tumor suppressive role of PTENP1 as a ceRNA in GC and identified the specific miRNAs decoyed by PTENP1, highlighting the emerging roles of ceRNAs in the biological regulation of GC cells and their possible clinical significance." (PMID 28212532, 2017). "Thus, PTENP1 modulates PTEN expression via PTENP1∼miR-106b/miR-93∼PTEN ceRNA network, allowing for PTENP1 to play a tumor-suppressive role in GC cells." (PMID 28212532, 2017).
tumor (continued). "Thus, we revealed a tumor suppressive role of PTENP1 as ceRNA in GC and pinpointed the specific miRNAs decoyed by PTENP1, highlighting the emerging roles of ceRNAs in the biological regulation of GC cells and their possible clinical significance." (PMID 28212532, 2017). "Overexpression of PTENP1 significantly inhibited the proliferation, colony formation and migration of HNSCC cells and xenograft tumour growth, suggesting that that PTENP1 may be a novel therapeutic and prognostic target for HNSCC." (PMID 28112249, 2017). "Moreover, we discovered that the PTENP1 expression level was notably related to tumor size (P < 0.05) and TNM (tumor-regional lymph node-metastasis) stage (P < 0.05) in HCC patients." (PMID 29296207, 2017). "Altogether, these results indicated that PTENP1 might act as a tumor suppressor by endogenously competing with miR-193a-3p, recovering the suppressed function of PTEN in HCC." (PMID 29296207, 2017). "Thus, PTENP1 exerts its tumor suppressive function as a ceRNA through distinct molecular mechanisms in different cancer types." (PMID 28212532, 2017). "Therefore, C/EBPβ 3′UTR did not affect the expression of the full-length C/EBPβ mRNA, indicating a difference in mechanism with the PTENP1 tumor suppressor gene pseudogene." (PMID 21283634, 2011). "Given that these studies focused on the existence of low levels of PTENP1 in cancer and its activity as a tumor suppressor, we expect it to be a promising candidate biomarker for the early detection of cancer in the future, as its reduced expression may predict poor prognosis for various tumors." (PMID 40877546, 2025). "In addition to its regulation of PTEN expression, PTENP1 is able to act as a tumour suppressor independent of its PTEN regulatory function as described in a recent review of the role of PTENP1 in human disorders with a focus on its tumour suppressor functionality." (PMID 37894321, 2023). "Another previous study illuminated that lower expression of PTENP1 in GC tissues or cell lines could be partly correlated with DNA hypermethylation, and it was related to larger tumor size, more advanced TNM staging, deeper invasion depth, and lymph node metastasis." (PMID 28931965, 2017). "Conversely, PTENP1 overexpression in ER-positive cancer cells (MCF-7/T-47D) led to decreased PTEN expression and tumor growth in these cells." (PMID 40877546, 2025). "PTEN mRNA levels can also be indirectly increased by delivering PTENP1 through rod-shaped viruses or small vesicles to act as sponges for miRNAs, thereby allowing PTEN to function freely in reducing tumor growth and inducing apoptosis in cancer cells." (PMID 40877546, 2025). "Blocking the recruitment of EZH2 upregulated the tumor suppressors PTENP1 and PTEN contributing to the reduction in breast cancer cell proliferation and tumor growth seen in xenograft mouse models." (PMID 41327312, 2025). "When PTENP1 was overexpressed in ER-negative cancer cells (MDA-MB-231/C3HBA), it increased PTEN expression and inhibited tumor progression." (PMID 40877546, 2025). "For example, lncRNA phosphatase and tensin homolog pseudogene 1 (PTENP1) is a competing endogenous RNA, which exerts its tumor suppressor function by regulating the expression of PTEN in many malignant tumors." (PMID 38994350, 2024). "PTENP1 upregulation acted to decrease the PTEN gene expression and to accelerate MCF7 tumor growth in vivo in both ER-positive cell lines." (PMID 38277283, 2024). "When PTENP1 was overexpressed in ER-positive breast cancer cells (MCF-7 and T-47D), PTEN expression decreased, and tumour growth was reported to be accelerated in MCF-7 cells." (PMID 37894321, 2023). "Contrastingly, overexpression of PTENP1 in ER-negative breast cancer cells (MDA-MB-231 and C3HBA), led to increased PTEN expression and inhibition of tumour progression." (PMID 37894321, 2023).
tumor (continued). "Previous studies revealed the role of PTENP1 as a ceRNA to trap microRNAs and consequently relieve their inhibition to the mRNA of the PTEN, a well-characterized tumor suppressor." (PMID 34065631, 2021). "For instance, PTENP1 regulates its parent gene PTEN, a tumor suppressor in human carcinoma, to inhibit the growth of tumor cells and plays an important role in the initiation and progression of HNSCC." (PMID 33931030, 2021). "Our final panel consisted of seven up‐regulated DElncRNAs (CCAT1, CCAT2, H19, HOTAIR, HULC, MALAT1, PCAT1), which were also known as oncolncRNAs and three down‐regulated lncRNAs (MEG3, PTENP1, and TUSC7) as tumor suppressor lncRNAs (tslncRNAs)." (PMID 33094859, 2021). "The processed pseudogene PTENP1 is involved in the regulation of the expression of the PTEN and acts as a tumor suppressor in many types of malignances." (PMID 33481830, 2021). "Taking into account the experimental evidence of its involvement in tumor development and progression, either regulating PTEN or other genes, PTENP1 can be considered a tumor suppressor." (PMID 32967233, 2020). "High PTENP1 level impeded the migratory and invasive capability of MDA-MB-231 cell compared to the cell transfected with vector, further demonstrating a tumor suppressive role of PTENP1 in BC cells." (PMID 31196157, 2019). "In conclusion, both PTENP1 and PTEN can serve as tumor suppressors and reduces HNSCC tumorigenicity." (PMID 29416703, 2018). "The PTENP1 pseudogene, as a key player in PTEN regulation, has the potential to strongly influence tumour development and progression." (PMID 29455665, 2018). "Conversely, when PTENP1 is downregulated, more miRNAs are available to inhibit PTEN expression, facilitating tumor growth." (PMID 30326930, 2018). "Accumulating evidence has revealed that the expression levels of PTENP1 and PTEN are positively correlated, and both are significantly down-regulated in HNSCC cell lines compared with adjacent non-tumor cells." (PMID 29416703, 2018). "Long non-coding RNA PTENP1, the pseudogene of PTEN tumor suppressor, has been reported to exert its tumor suppressive function via modulation of PTEN expression in many malignancies." (PMID 28212532, 2017). "PTENP1, a pseudogene of PTEN, was previously reported to be a tumour suppressor in some cancer types." (PMID 28112249, 2017). "Because PTEN was reported to be the target gene protected by PTENP1, we also detected the expression of PTEN in tumour cells." (PMID 28112249, 2017). "PTENP1 has been reported to modulate PTEN expression via PTENP1∼miRNA∼PTEN ceRNA network, thereby exerting its tumor suppressive functions in a variety of malignancies." (PMID 28212532, 2017). "Long non-coding RNA PTENP1, the pseudogene of PTEN tumor suppressor, was previously reported to be a tumour suppressor in some cancer types." (PMID 29296207, 2017). "PTENP1 regulates cellular levels of PTEN by both sense and antisense RNAs which act as decoys for PTEN targeting microRNAs and also exert tumor-suppressive activities." (PMID 29206165, 2017). "For instance, lncRNA PTENP1, a pseudogene of PTEN, was verified to function as a tumor suppressor in some cancer types, including GC." (PMID 28931965, 2017). "In order to identify and characterize the PTENP1∼miRNA∼PTEN ceRNA network, we determined PTENP1 levels in clinical GC biopsies and revealed that PTENP1 and PTEN were concurrently downregulated in the tumor tissues." (PMID 28212532, 2017). "Significantly, the 3′UTR of PTENP1, a pseudogene homologous to the tumor suppressor gene PTEN, was found to exert tumor suppressor activity though removing some miRNA that down-regulates the expression of PTEN, thus liberating the expression of the latter." (PMID 21283634, 2011).
tumor (continued). "Examples include nanoparticles containing PTEN mRNA, which directly restore PTEN levels in the cell, and rod-shaped viruses or nanovesicles containing PTENP1/lncRNA, which indirectly increase PTEN mRNA levels by acting as sponges for miRNAs, thereby resulting in tumor suppression." (PMID 40877546, 2025). "In addition, most lncRNAs are up-regulated to sponge microRNAs and promote cancer development and progression, while, some of them are down-regulated and act as tumor suppressors; these include lncRNAs STXBP5-AS1, TUSC8, PTENP1, and CASC2." (PMID 34703793, 2021). "In addition, the PTENP1 transcript was found to act as a ceRNA, protecting the parental gene PTEN from miR-21 binding and therefore inhibiting tumor cell proliferation and colony formation." (PMID 34440428, 2021). "However, in ER-negative breast cancer cells, PTENP1 upregulation increased PTEN mRNA expression and inhibited tumor progression." (PMID 32314732, 2020). "The first report of the ceRNA in cancer is phosphatase and tensin homolog pseudogene 1 (PTENP1), a pseudogene of phosphatase and tensin homolog (PTEN), and it showed tumor suppressive effect by binding miRNAs such as miR-17, miR-19, and miR-21 which were ultimately targeting PTEN." (PMID 32906679, 2020). "Although the expression of PTEN and PTENp1 is generally downregulated in tumor cells, it has been found that the promoter that is methylated in tumor cells is mainly that of PTENp1 not PTEN." (PMID 31656200, 2019). "Furthermore, ectopic PTENP1 expression inhibited the proliferation, colony formation and migration of HNSCC cells and the growth of xenograft HNSCC tumours." (PMID 28112249, 2017). "Furthermore, there was a low expression level of PTENP1 and a high expression level of miR-193a-3p in HCC tissues, which related to tumor size and TNM stage, leading to a poor prognosis." (PMID 29296207, 2017). "No survival difference was observed between patients with tumor PTENP1 gene expression above or below the median within the pooled cohort of patients with stage 3 disease, nor within any of the subgroups (Online Resource 4)." (PMID 28213783, 2017). "An example is PTENP1 which is the pseudogene of PTEN, a well-characterized tumor suppressor." (PMID 29206165, 2017). "The current studies about GC mainly focused on the effects of lncRNA PTENP1 on tumor progression, not covering gastric carcinogenesis." (PMID 28931965, 2017). "Functionally, PTENP1 was found to have tumor suppressive activity and was selectively lost in human cancer, which suggest a potential role of this pseudogene in the normal functioning of PTEN in tumor suppression." (PMID 25539629, 2014). "In their study, the authors demonstrated that PTENP1 modulates endogenous PTEN transcript levels by acting as a molecular sponge for PTEN-targeting miRNAs; thus, the PTENP1 transcript serves as an effective decoy and exerts tumor suppressive functions." (PMID 24013378, 2013). "Moreover, PTENP1, functioning analogously to MEG3 in bladder cancer, enhances the expression of tumor suppressors like PDCD4 by suppressing miR-20a, thereby inhibiting tumor growth and metastasis." (PMID 40242248, 2025). "On the contrary, other lncRNAs, such as the phosphatase and tensin homolog pseudogene 1 (PTENP1), which has been found downregulated in HCC, could act as tumor suppressors by activating autophagy and promoting autophagic cell death of tumor cells and inhibiting migration, invasion, and angiogenesis." (PMID 35159028, 2022). "Of note, even in the absence of PTEN, PTENP1 still exhibited a tumour suppressive function." (PMID 28112249, 2017). "However, the positive correlation between PTEN and PTENP1 transcript levels established in the current report, and the known tumor inhibitory role of PTENP1, do not indicate that the negative prognostic impact of high PTEN levels is mediated via its pseudogene." (PMID 28213783, 2017).
tumor (continued). "In contrast, in the ER-negative breast cancer cells, upregulation of PTENP1 increases PTEN gene expression with no influence on miR-26a or ERα expression, but is able to reduce tumor metastasis in a xenograft model." (PMID 30071685, 2018). "A decrease in the PTENP1 copy number, but not in the PTEN copy number, was frequently observed in tumour cell lines (4 of 5 cell lines) by genomic real-time PCR." (PMID 28112249, 2017).